KNSTRN (kinetochore localized astrin (SPAG5) binding protein)
Description:
Essential component of the mitotic spindle required for faithful chromosome segregation and progression into anaphase. Promotes the metaphase-to-anaphase transition and is required for chromosome alignment, normal timing of sister chromatid segregation, and maintenance of spindle pole architecture. The astrin (SPAG5)-kinastrin (SKAP) complex promotes stable microtubule-kinetochore attachments. Required for kinetochore oscillations and dynamics of microtubule plus-ends during live cell mitosis, possibly by forming a link between spindle microtubule plus-ends and mitotic chromosomes to achieve faithful cell division. May be involved in UV-induced apoptosis via its interaction with PRPF19; however, these results need additional evidences.
Synonyms: SKAP; Kinastrin; C15orf23; TRAF4AF1; HSD11; FLJ14502; ROCHIS
Tractability: Antibody: its Gene Ontology location is reachable by antibodies, with high confidence. PROTAC: ubiquitination databases record sites on it.
Gene: Protein-coding gene on chromosome 15 (40,382,721 to 40,394,288, forward strand). Ensembl gene ENSG00000128944.
Subcellular location: Nucleus; Chromosome, centromere, kinetochore; Cytoplasm, cytoskeleton, spindle pole; Cytoplasm, cytoskeleton, microtubule organizing center
Subcellular location (Human Protein Atlas): Centriolar satellite; Mitotic spindle; Plasma membrane
Gene Ontology:
Molecular function: microtubule plus-end binding; protein binding; protein homodimerization activity
Biological process: cell migration; cellular response to epidermal growth factor stimulus; chromosome segregation; microtubule cytoskeleton organization; mitotic sister chromatid segregation; regulation of attachment of spindle microtubules to kinetochore; spindle organization
Cellular component: centriolar satellite; kinetochore; microtubule organizing center; microtubule plus-end; mitotic spindle; nucleus; ruffle; spindle pole
Genetic constraint (gnomAD): Loss-of-function variants: 31 observed, 37.73 expected, observed/expected ratio (o/e) 0.82, 90% interval 0.62 to 1.11. The upper end of that interval is the gene's LOEUF score, 1.11, which puts it in group 4 of 6, group 1 being the genes least tolerant of losing a copy. Missense variants: 381 observed, 368.14 expected, observed/expected ratio (o/e) 1.03, 90% interval 0.95 to 1.13. Synonymous variants: 151 observed, 149.84 expected, observed/expected ratio (o/e) 1.01, 90% interval 0.88 to 1.15.
Homologues: Orthologues: chimpanzee KNSTRN (99% identical), macaque KNSTRN (95% identical), pig KNSTRN (76% identical), mouse Knstrn (68% identical), rat Knstrn (65% identical), rabbit KNSTRN (55% identical), guinea pig KNSTRN (53% identical), tropical clawed frog knstrn (18% identical), zebrafish knstrn (14% identical).
Diseases named in the same sentence as KNSTRN in open-access papers:
KNSTRN is named in the same sentence as 46 diseases in open-access papers, as found by Europe PMC text mining. Sharing a sentence is not in itself a finding about the gene and the disease. The quoted sentences say what the papers report.
melanoma (7 papers, 2019 to 2025). A malignant, usually aggressive tumor composed of atypical, neoplastic melanocytes. "This mutation cluster targeting nucleotides 4–103 of the KNSTRN reference transcript was confirmed when analyzing melanoma samples in COSMIC, and the mutations were detected in 4.4%–5.5% of melanoma tumors (46/1,034 in COSMIC and 26/470 in TCGA-SKCM)." (PMID 40359938, 2025). "Intriguingly, chr15:40382906 C > T resides upstream of the expressed KNSTRN transcripts in melanoma, and it is part of a cluster of noncoding mutations in the KNSTRN promoter region." (PMID 41278537, 2025). "In KNSTRN, we identified an intriguing cluster of non-coding promoter mutations present in 4.4%–5.5% of melanoma cases." (PMID 40359938, 2025). "To verify which of these transcripts are expressed in SKCM, we mapped RNA-seq data from KNSTRN wild-type and mutated melanoma to the genome." (PMID 40359938, 2025). "In all analyzed melanomas, the identified mutations were located upstream of the expressed KNSTRN transcripts." (PMID 40359938, 2025). "Subsequent analysis of The Cancer Genome Atlas (TCGA) datasets showed that the KNSTRN mutations also occur in 5% of melanoma samples but are rare in other cancers." (PMID 34900699, 2021). "Furthermore, recent studies demonstrated that accumulation of KNSTRN mutations may be an early event in cancer development that accelerates tumor growth in cutaneous squamous cell carcinoma and melanoma." (PMID 34568334, 2021). "KNSTRN is also frequently somatically mutated in basal cell carcinoma in addition to cutaneous SCC and melanoma, although this mutation usually occurs in advanced stages of the tumor." (PMID 36845017, 2023). "Whereas chr15:40382906 C > T indeed corresponds to a KNSTRN p.Ser24Phe mutation in respect to reference transcript KNSTRN-201, analysis of RNA-seq data from human melanoma tumors revealed that this transcript is not expressed in melanoma." (PMID 41278537, 2025). "This variant was first reported in 2014 as a missense p.Ser24Phe substitution in KNSTRN and was described in 19% of cutaneous squamous cell carcinomas (SCCs), a less aggressive skin cancer subtype derived from keratinocytes, as well as in 5% of melanoma tumors." (PMID 41278537, 2025). "They search of publicly available TCGA data suggests KNSTRN might also play a role in melanoma." (PMID 31781484, 2019). "This, for instance, applies to the mutation clusters targeting known cancer genes kinetochore localized astrin (SPAG5) binding protein (KNSTRN) and BCL2-like 12 (BCL2L12), each affecting 4%–5% of melanoma tumors." (PMID 40359938, 2025). "Moreover, they searched TCGA database, suggesting that KNSTRN might also play a role in melanoma." (PMID 33976733, 2021). "KNSTRN expression levels were not significantly different between melanoma tumors with a wild-type or mutant KNSTRN promoter status, which may be due to the limited number of mutated tumors for which expression data were available." (PMID 40359938, 2025).
bladder cancer (5 papers, 2022 to 2025). "KNSTRN also contributes to therapy resistance potentially through ER stress pathways in bladder cancer, and its genetic variants underscore its potential as a diagnostic and therapeutic target." (PMID 41209020, 2025). "Kinetochore-localized astrin/SPAG5-binding protein (KNSTRN) promotes the progression of bladder cancer and lung adenocarcinoma." (PMID 38198023, 2024). "In bladder cancer, KNSTRN affects the cell cycle by regulating the expression of cyclin D1 and CDK2." (PMID 38198023, 2024). "This is consistent with previous reports that KNSTRN is highly expressed in bladder cancer." (PMID 36845017, 2023). "For example, KNSTRN promotes tumorigenesis and gemcitabine resistance in bladder cancer." (PMID 36010660, 2022). "The role of KNSTRN in tumors involves the promotion of tumorigenesis and gemcitabine resistance through the activation of AKT (also known as protein kinase B) in bladder cancers." (PMID 38198023, 2024). "KNSTRN, a component of the mitotic spindle, phosphorylates AKT at Thr308 and Ser473 to activate AKT and promote bladder cancer metastasis." (PMID 37143582, 2023). "KNSTRN promotes the movement of AKT to PIP3 and stimulates AKT phosphorylation, resulting in metastasis and gemcitabine resistance in bladder cancer." (PMID 36845017, 2023). "KNSTRN phosphorylates AKT at Thr308 and Ser473 to activate AKT and promotes bladder cancer metastasis." (PMID 37143582, 2023).
lung adenocarcinoma (5 papers, 2021 to 2025). A carcinoma that arises from the lung and is characterized by the presence of malignant glandular epithelial cells. "In lung adenocarcinoma, high KNSTRN levels are positively associated with Th2 cells and markers of T-cell exhaustion (including PD-1, CTLA-4, and LAG-3)." (PMID 41209020, 2025). "This study aimed to evaluate the prognostic value of KNSTRN in lung adenocarcinoma (LUAD) underlying the Cancer Genome Atlas (TCGA) database." (PMID 33976733, 2021). "Only an analysis of lung adenocarcinoma identified a positive correlation between KNSTRN expression and the levels of Th2 and CD56dim NK cells, which highlights the potential role of KNSTRN in tumor immunity." (PMID 36845017, 2023). "We found that overexpression of these 8 genes (CENPA, FAM83D, KNSTRN, CDKN3, CCNB1, CDK1, and CCNA2) is significantly associated with poor survival of lung adenocarcinoma patients (p-value < 0.05)." (PMID 36291764, 2022). "Recent research has identified KNSTRN as a potential oncogene involved in the progression of various cancers, including cutaneous squamous cell carcinoma, hepatocellular carcinoma, lung adenocarcinoma." (PMID 41209020, 2025). "Studies on KNSTRN have mainly focused on somatic mutations, and research on the involvement of KNSTRN in tumor immunity remains scarce, even though KNSTRN has been shown to have a significant influence on immune cells in the tumor microenvironment of lung adenocarcinoma (LUAD)." (PMID 36845017, 2023).
cutaneous squamous cell carcinoma (4 papers, 2017 to 2025). "Point mutations in KNSTRN are described in cutaneous squamous cell carcinoma." (PMID 29312620, 2017).
endometrial cancer (4 papers, 2019 to 2021). Primary or metastatic malignant neoplasm involving the endometrium (mucous membrane that lines the endometrial cavity). "KNSTRN is significantly associated with dismal survival status in endometrial cancer." (PMID 34260414, 2021). "Moreover, in a recent study on endometrial cancer, it was found that the expression of KNSTRN was positively correlated with AKT1, and high expression of KNSTRN was significantly associated with poor prognosis of endometrial cancer." (PMID 33976733, 2021). "In addition, the data also shows that the higher expression of AKT1, GTSE1, BIRC5, AURKA, and KNSTRN is significantly associate with poor prognosis of endometrial cancer." (PMID 31781484, 2019). "Moreover, the data also shows that the higher expression of AKT1, GTSE1, BIRC5, AURKA, and KNSTRN is significantly associate with poor prognosis of endometrial cancer." (PMID 31781484, 2019). "However, the role of KNSTRN in endometrial cancer was rarely be reported." (PMID 31781484, 2019). "We selected the six hub genes (GTSE1, BIRC5, AURKA, PBK, KNSTRN, and PSMB10) and AKT1 to evaluate gene expression values in endometrial cancer using IHC." (PMID 31781484, 2019).
breast carcinoma (3 papers, 2015 to 2025). "Kaplan–Meier survival analyses demonstrated a significant association between high expression of KNSTRN and poor overall survival, relapse-free survival, post-progression survival, and distant metastases-free survival in patients with breast cancer." (PMID 38198023, 2024). "Our findings indicate that elevated expression of KNSTRN is significantly associated with an unfavorable prognosis and serves as an independent prognostic factor in patients diagnosed with breast cancer." (PMID 38198023, 2024). "To investigate the association between KNSTRN expression and the prognosis of patients with breast cancer, we performed a survival analysis using the Kaplan–Meier method." (PMID 38198023, 2024). "Moreover, KNSTRN has potential as a molecular biomarker for diagnostic and prognostic prediction in breast cancer." (PMID 38198023, 2024). "KNSTRN mutations were significantly associated with poor prognosis in patients with breast cancer." (PMID 38198023, 2024). "Furthermore, according to ROC curve analysis, KNSTRN is a potential diagnostic biomarker for breast cancer (AUC = 0.879)." (PMID 38198023, 2024). "Consequently, KNSTRN exhibits promising prospects as a diagnostic and prognostic marker for monitoring patients with breast cancer." (PMID 38198023, 2024). "Additionally, our findings revealed a significant association between high KNSTRN expression and unfavorable overall survival, relapse-free survival, post-progression survival, and distant metastasis-free survival in patients with breast cancer." (PMID 38198023, 2024). "The limited availability of data on KNSTRN mutations in breast cancer patients necessitates further investigation into the detection of KNSTRN alleles in large clinical samples, identification of mutation types and loci, and elucidation of variable splicing patterns in KNSTRN transcripts." (PMID 38198023, 2024). "KNSTRN was significantly overexpressed in TNBC compared to those in other breast cancer subtypes and normal tissues." (PMID 41209020, 2025). "We aimed to investigate the diagnostic and prognostic values of KNSTRN in breast cancer patients, explore its correlation with immune infiltration, and demonstrate the effect of KNSTRN on the proliferation of breast cancer cells." (PMID 38198023, 2024). "We then analyzed the relationship between KNSTRN expression and the outcome of patients with breast cancer in different clinical subgroups." (PMID 38198023, 2024). "Inhibition of KNSTRN expression not only leads to cell cycle arrest at the G1-S transition but also diminishes the proliferative capacity of breast cancer cells." (PMID 38198023, 2024). "By increasing the expression of these proteins, KNSTRN is evidently involved in different phases of the cell cycle and, thus, promotes the proliferation of breast cancer cells." (PMID 38198023, 2024). "The findings revealed a significant increase in both mRNA and protein expression levels of KNSTRN among breast cancer patients compared to their adjacent tissues." (PMID 38198023, 2024). "The overexpression and silencing of KNSTRN in vitro, respectively, promoted and inhibited the proliferation of breast cancer cells." (PMID 38198023, 2024). "Our findings revealed a significant and inverse correlation between elevated KNSTRN expression and overall survival (OS), relapse-free survival, post-progression survival, as well as distant metastasis-free survival in breast cancer patients." (PMID 38198023, 2024). "In the single-cell transcriptomic profile of breast cancer, KNSTRN was significantly and positively correlated with the cell cycle, DNA damage, proliferation, and DNA repair at the single-cell level." (PMID 38198023, 2024). "The results from the analysis of the GEO dataset (No. GSE42587) further validated the higher mRNA expression of KNSTRN in the breast cancer tissues (p < 0.001)." (PMID 38198023, 2024).
breast carcinoma (continued). "To investigate the correlation between KNSTRN expression and clinical characteristics in breast cancer patients, we conducted an analysis of KNSTRN mRNA expression levels across different TCGA clinical categories." (PMID 38198023, 2024). "Univariate Cox analysis showed that age (p < 0.0001) and pTNM-stage (p < 0.0001) were significantly correlated with OS in breast cancers, whereas KNSTRN expression was almost significantly correlated with OS in breast cancers (p = 0.05308)." (PMID 38198023, 2024). "The expression profile of KNSTRN in single cells of breast cancer suggested that KNSTRN was highly expressed in breast cancer cells at the single-cell level." (PMID 38198023, 2024). "In conclusion, our study demonstrates that KNSTRN functions as an oncogene in breast cancer by regulating immune response, promoting G1/S transition, and facilitating breast cancer cell proliferation." (PMID 38198023, 2024). "Survival curves suggested that SNVs of KNSTRN in breast cancer were significantly and negatively correlated with OS, progression-free survival, and disease-free interval." (PMID 38198023, 2024). "To further investigate the mechanisms by which KNSTRN expression is abnormally upregulated in breast cancer tissues, we examined the relationship between KNSTRN methylation and expression levels using DiseaseMeth, version 3.0." (PMID 38198023, 2024). "Analyses of The Cancer Genome Atlas, Gene Expression Omnibus, TIMER, and The Human Protein Atlas databases revealed a significant upregulation of KNSTRN transcript and protein levels in breast cancer." (PMID 38198023, 2024). "Ultimately, our findings demonstrate that KNSTRN is a potential biomarker for the diagnosis and prognosis of breast cancer due to immune infiltration and proliferation within the context of breast cancer." (PMID 38198023, 2024). "Twenty pairs of paired tumor and adjacent human tissue samples were used to detect the mRNA and protein expression levels of KNSTRN in patients with breast cancer." (PMID 38198023, 2024). "Notably, elevated KNSTRN expression was observed in a range of cancers including breast cancer (BRCA)." (PMID 41209020, 2025). "Therefore, KNSTRN represents a promising biomarker for both diagnosis and prognosis assessments in breast cancer." (PMID 38198023, 2024). "To validate the effect of KNSTRN on the cell cycle and cell proliferation in breast cancer cells, we measured the proliferative phenotypes and the expression of cell cycle regulators in breast cancer cells." (PMID 38198023, 2024). "Furthermore, multivariate Cox regression analyses confirmed that KNSTRN is an independent prognostic factor for breast cancer." (PMID 38198023, 2024). "Moreover, KNSTRN functions as an oncogene specific to breast cancer, whereby its heightened expression expedites G1/S transition and fosters cellular proliferation." (PMID 38198023, 2024). "Based on the findings of the mRNA, protein, prognostic, and immune infiltration analyses of KNSTRN, our hypothesis is that KNSTRN plays an oncogenic role in breast cancer." (PMID 38198023, 2024). "The collective findings suggest that KNSTRN exhibits high expression levels across various cancer types, including breast cancer, thereby indicating its potential as a pathological biomarker for the accurate diagnosis of breast cancer." (PMID 38198023, 2024). "Therefore, we investigated the correlation between KNSTRN expression and immune infiltration in breast cancer across multiple GEO datasets." (PMID 38198023, 2024). "The expression of KNSTRN in breast cancer cell lines was assessed by western blotting." (PMID 38198023, 2024). "We conducted an analysis of KNSTRN expression levels in various types of cancers using the TIMER database and observed a significant upregulation of KNSTRN expression in several tumors, including bladder urothelial carcinoma, breast cancer, and cholangiocarcinoma." (PMID 38198023, 2024).